TPO (thyroid peroxidase)
Diseases named in the same sentence as TPO in open-access papers (continued):
Sharing a sentence is not in itself a finding about the gene and the disease.
hypothyroidism (continued). "These risks are more pronounced in severe cases of hypothyroidism and may also be elevated in women with thyroid peroxidase (TPO) antibodies." (PMID 39941206, 2025). "We show that the highest predictive accuracy for hypothyroidism was achieved when combining the PRS with thyroid hormones and thyroid-peroxidase autoantibodies, and that the PRS was able to stratify risk of progression among individuals with subclinical hypothyroidism." (PMID 41238958, 2025). "Hypothyroidism has been associated with reduced HRQoL, particularly in areas such as sleep and social isolation, regardless of TPO-Ab levels." (PMID 40355879, 2025). "It was observed that anti-TPO antibodies, but not anti-Tg antibodies, associated with hypothyroidism were found to be more frequent in SSc patients compared to controls." (PMID 38256549, 2024). "Therefore, the total number of patients included for hypothyroidism was 6,035 (four articles), anti-TPO, 6,069 (four articles), anti-TG, 443 (three articles), altered TSH, 96 (one article), and mean TSH, 6,071 (four articles)." (PMID 37598033, 2024). "Biochemically, HT in T21 begins earlier than in healthy controls and most commonly starts with subclinical hypothyroidism that may evolve to overt hypothyroidism because of the presence of anti-thyroid antibodies (anti-TPO, anti-Tg)." (PMID 39795885, 2024). "Expectedly, individuals with hypothyroidism are more likely to be positive for anti-TPO antibodies." (PMID 38946973, 2024). "HT is characterized by hypothyroidism in various degrees, the presence of lymphocytic infiltrates, follicular lesions, or fibrosis at glandular level, as well as in the serum detection of antibodies against thyroid peroxidase (TPO) and thyroglobulin (Tg)." (PMID 38672712, 2024). "The results already published from our RCT showed that total thyroidectomy has a beneficial effect for patients with Hashimoto disease and anti-TPO antibody level >1000 IU/mL and persistent symptoms despite adequate thyroid hormone substitution for hypothyroidism." (PMID 38606313, 2024). "Not all women with TS developed hypothyroidism but those with elevated TPO antibodies were at highest risk." (PMID 37758506, 2024). "Indeed, 62% of individuals with history of hypothyroidism were TPO+, whereby anti-TPO is just one of the possible autoantibodies associated with AITD." (PMID 38946973, 2024). "As one of the most common autoimmune disorders in the world, Hashimoto’s thyroiditis (HT) is characterized by lymphocyte infiltration and thyroid autoantibodies such as against thyroid peroxidase (anti-TPO) or thyroglobulin (anti-TG), which eventually leads to thyroid fibrosis and hypothyroidism." (PMID 38803479, 2024). "High ANA titer and hypothyroidism (generally accompanied by anti-thyroid peroxidase antibody) are commonly observed in patients with RPL; however, their presence does not serve as a predictor of subsequent miscarriages, and their role in RPL pathogenesis is controversial." (PMID 39019884, 2024). "No statistical significance in the detection rate of clinical hyperthyroidism, subclinical hyperthyroidism, clinical hypothyroidism, subclinical hypothyroidism, goiter, thyroid nodule, and TPO Ab positive ratio of different iodine nutrition conditions (P > 0.05)." (PMID 37745704, 2023). "Moreover, the risk of miscarriage was approximately quadrupled in women with coexisting overt hypothyroidism and positive anti-TPO." (PMID 37606882, 2023). "Moreover, several studies have established a higher prevalence of thyroid dysfunction, particularly overt hypothyroidism, anti-TPO positivity, and AITD among RA patients." (PMID 37798692, 2023). "Additionally, it would be clinically important to evaluate the utility of anti-thyroid peroxidase (TPO) antibody levels as a measure or predictor of RT-induced hypothyroidism." (PMID 37686597, 2023).
hypothyroidism (continued). "A 50-year-old woman with myxedema was diagnosed with Hashimoto's disease due to hypothyroidism and the presence of antibodies against thyroid peroxidase (TPOAb) and thyroglobulin (TgAb); she also had thyroid stimulating antibodies (TSAb) without any signs of GD." (PMID 37109715, 2023). "Likewise, hypothyroidism following surgery for Graves’ disease was more likely to occur with an anti-TPO Abs titer of ≤20 IU/mL (odd ratio = 6.8, sensitivity = 67%, specificity = 77%, p=0.003)." (PMID 37123800, 2023). "Additionally, their anti-TPO Ab levels were significantly lower than those in patients with hyperthyroidism and hypothyroidism (both P < 0.001 after adjustment for sex and age at APS diagnosis)." (PMID 37878416, 2023). "Thyroid peroxidase antibodies (anti-TPO) may further aggravate the impact of hypothyroidism on the incidence of complications during pregnancy, including miscarriage and premature delivery." (PMID 37869413, 2023). "The patient also suffered from diabetes mellitus and hypothyroidism (elevated TPO antibodies)." (PMID 35493848, 2022). "In this study, we hypothesize that a positive TPO Ab status prior to the first administration of RAI in patients with Graves’ disease increases the incidence of post RAI hypothyroidism." (PMID 35687484, 2022). "We investigated whether a positive thyroid peroxidase antibody (TPO Ab) status before radioactive iodine (RAI) therapy in patients with Graves’ hyperthyroidism is a predictive factor for developing hypothyroidism post RAI." (PMID 35687484, 2022). "Hence, we propose that decreased expression of ferritin, hypochlorhydria, and decreased TPO activity are the possible mechanisms for hypothyroidism-induced IDA in pregnancy." (PMID 36158423, 2022). "Another factor that might also affect QOL in individuals treated for hypothyroidism is the presence of thyroid peroxidase (TPO) antibodies." (PMID 35966075, 2022). "In this multicentric retrospective study, we investigated if the TPO Ab status in patients with Graves’ disease prior to the first administration of RAI plays a role in the incidence of hypothyroidism and cure, defined ascombined hypothyroidism and euthyroidism." (PMID 35687484, 2022). "Mechanisms that underlie autoimmune thyroiditis and involve attacking the thyroid gland by autoreactive lymphocytes and autoantibodies against thyroid peroxidase (anti-TPO) and thyroglobulin (anti-TG) lead to impaired production of thyroid hormones and hypothyroidism." (PMID 36431248, 2022). "Positive TPO has been described as an early predictor of hypothyroidism so it is plausible that some of these individuals may develop thyroid disorder within a few years." (PMID 35668375, 2022). "In case of hypothyroidism, TPO-antibody testing is recommended as it indicates autoimmune etiology." (PMID 36149449, 2022). "Furthermore, several studies reported that the presence of both anti-thyroid peroxidase antibody at baseline and anti-thyroglobulin antibody during the therapy was significantly correlated to hypothyroidism development." (PMID 36612243, 2022). "Women with elevated TPO-AB had a significantly higher prevalence of hypothyroidism (p < 0.001)." (PMID 35453500, 2022). "Since anti-TPO or anti-TG antibodies were well known risk factors for hypothyroidism, we analyzed ARD patients with or without those antibodies separately." (PMID 34226611, 2021). "Anti‐TPO also plays a role in predicting progression to overt hypothyroidism." (PMID 33817980, 2021). "Considering the change in the obesity phenotype during follow-up and the potential confounding factors associated with thyroid function such as age and TPO-Ab, we utilized GEE analysis to further evaluate the relationship between obesity phenotypes and hypothyroidism in this cohort study." (PMID 33818715, 2021).
hypothyroidism (continued). "The appearance of anti-thyroid peroxidase antibodies (anti-TPO) is considered as a predictive factor that indicates the transition of subclinical hypothyroidism into overt hypothyroidism, observed in approximately 20–30% of patients with autoimmune thyroiditis." (PMID 34576041, 2021). "Autoantibodies for thyroid glands, such as TPO-Ab and Tg-Ab, would be excellent biomarkers for autoimmune thyroiditis, and euthyroid patients with TPO-Ab and/or Tg-Ab should be carefully followed up with regularly repeated thyroid function because of the risks for evolving hypothyroidism." (PMID 34887872, 2021). "In conclusion, unlike anti-TPO positivity, ultrasonographic findings were not identified as a risk factor for recurrence and permanent hypothyroidism." (PMID 32555998, 2020). "In the current study, anti-TPO positivity was detected as a risk factor for permanent hypothyroidism, whereas bilateral or unilateral disease involvement was not an indicator of recurrence or permanent hypothyroidism." (PMID 32555998, 2020). "Aetiological diagnosis may require anti-antiperoxidase (thyroid peroxidase (TPO)) antibodies for hypothyroidism and anti-TSH receptor antibodies, thyroid scintigraphy and/or doppler ultrasound in hyperthyroidism." (PMID 33228219, 2020). "The presence of antibodies to thyroid peroxidase (TPO-Ab) or thyroglobulin in pregnancy is associated with significant increase in miscarriages, premature deliveries, gestational diabetes, postpartum thyroiditis and permanent hypothyroidism." (PMID 33302910, 2020). "Of the eight patients who developed hypothyroidism, six (75%) had both elevated anti-Tg and anti-TPO antibodies at baseline and pre-cycle 3, one patient (12.5%) developed elevated anti-Tg and anti-TPO titers at pre-cycle 3, and the last patient had non-elevated titers at both time points." (PMID 33299547, 2020). "Moreover, the incidence of hypothyroidism is higher in patients positively expressing TPO-Ab and TG-Ab." (PMID 32461982, 2020). "Clinicians should be aware of HPT dysfunction in ECD, and we recommend that all patients diagnosed with ECD be screened at baseline for hypothyroidism with measurements of thyrotropin, circulating thyroid hormones (fT4 and triiodothyronine [T3]), and anti-TPO antibodies." (PMID 33119105, 2020). "The presence of primary hypothyroidism in patients without TPO antibodies suggests a potentially unique cause of hypothyroidism in this population and forms a basis for further research studies on a functional role of HGA deposition in the thyroid gland." (PMID 32202644, 2020). "Similarly, thyroid peroxidase (TPO) and thyroglobulin antibody levels are associated with hypothyroidism in NSCLC patients receiving nivolumab treatment." (PMID 33072580, 2020). "Univariate binary logistic regression was performed with hypothyroidism or hyperthyroidism as dependent variable, TPO-abs or Tg-abs as independent variables and psychopharmaceutical treatment as covariant to explore the relationship between antithyroid antibodies and thyroid dysfunction." (PMID 31791284, 2019). "Anti-TPO antibody positivity and ibuprofen treatment were found to be significant variables in the Pearson Chi-square test to determine the risks of permanent hypothyroidism (p:0.03 and p:0.04, respectively)." (PMID 31729433, 2019). "The incidence of anti-TPO positivity seen earlier than the onset of subclinical/overt hypothyroidism in group A1 was significantly higher (p<0.0001) than the combined control group and anti-TPO was positive in an average of 252(±33) days ahead of the onset of subclinical/overt hypothyroidism." (PMID 31467701, 2019). "TPO-abs positivity was found to be significantly associated with hyperthyroidism (p < 0.001, OR = 8.872, 95%CI = 3.454–22.788) but not with hypothyroidism (p > 0.10)." (PMID 31791284, 2019).
hypothyroidism (continued). "Interestingly, other SNPs in this region have been associated with multiple other traits (e.g., leprosy, bacteremia, thyroid peroxidase antibody levels, and hypothyroidism), supporting the value of ShinyGPA to unveil novel pleiotropic relationships." (PMID 29309429, 2018). "Among vitamin D-deficient cases, an increased serum 25(OH)D ≥ 50 nmol/L was associated with greater reductions in biochemical signs of hypothyroidism and thyroid autoimmune disease including an increase in FT4 and FT3, and large decrease in serum TSH, anti-TPO, anti-TG, and TG." (PMID 29067607, 2017). "Hashimoto’s thyroiditis, which is a common autoimmune condition, may also lead to hypothyroidism by TPO-specific T cells and possibly TPO autoantibody-mediated damage by NK cells and activation of the complement cascade." (PMID 28620373, 2017). "It has been hypothesized that antibody production promotes progression to hypothyroidism because higher levels of antibodies against Tg and TPO accompany deterioration of thyroid function." (PMID 28536577, 2017). "In the Whickham follow-up study, women with TPO-Abs had an eight-fold higher risk of developing clinically overt hypothyroidism over 20 years than did antibody-negative women." (PMID 27092550, 2016). "Therefore the aim was to analyze presence of anti-TPO antibodies in hypothyroidism patients in Gujarat." (PMID 26963610, 2016). "According to Schott and Scherbaum an increased TSH level and clinical hypothyroidism were significantly associated with TPO antibodies, but not with Tg antibodies." (PMID 26000316, 2015). "Clinical diagnosis is based on the presence of diffuse goiter (or various clinical courses including euthyroidism with goiter, subclinical hypothyroidism with goiter, hypothyroidism, adolescent goiter), anti-thyroid peroxidase Ac, anti-Tg Ac or lymphocytic infiltration on cytological examination." (PMID 26327979, 2015). "Based on some studies treatment with Levothyroxine may attenuate the level of Anti TPO antibody in hypothyroid patients and patients whose hypothyroidism is due to Hashimoto’s disease may benefit more from Levothyroxine therapy." (PMID 25364704, 2014). "The increased values of anti-Neu5Gc antibodies in patients with hypothyroidism and the correlation of anti-TPO incidence with increased anti-Neu5Gc concentration raised the concept of a probable association between anti-Neu5Gc antibody development and autoimmune hypothyroidism." (PMID 25003133, 2014). "Many authors in literature believe that anti-TPO could play a role in the occurrence of foeto-maternal complications during pregnancy and therefore, there is an interest in screening for hypothyroidism around the pregnancy." (PMID 24497920, 2014). "Although sialic acids in the carbohydrate moieties of TG and TPO molecules could be substituted by Neu5Gc under certain conditions, it needs to be proved for the patients suffering from hypothyroidism." (PMID 25003133, 2014). "Thus, mutations in these regions are expected to have major effects on TPO activity resulting in severe organification defect and severe hypothyroidism." (PMID 24829575, 2014). "The relative risk of developing thyroid dysfunction, mainly hypothyroidism, was reported to betwo to 14 fold higher in patients with pre-existing positive TPO-Ab, as compared to patients with negative antibodies." (PMID 23383326, 2013). "In conclusion, although we were not able to confirm it by molecular analysis, we clinically diagnosed four siblings with congenital severe hypothyroidism due to impaired iodide organification and an accompanying congenital deafness owing to, probably, a TPO or other genetic defect." (PMID 21274344, 2010). "Indeed, high amounts of anti-thyroid peroxidase autoantibodies are found in the sera of patients suffering from Graves' disease and Hashimoto's thyroiditis, respectively hyper and hypothyroidism." (PMID 15769293, 2005). "Anti-TPO did not increase the risk of hypothyroidism post-ATD therapy." (PMID 40255503, 2025).
hypothyroidism (continued). "However, in this case, where thyroid hormone levels remained normal except for raised anti-TPO antibodies, undetected or underappreciated mild hypothyroidism or subclinical hypothyroidism may be a contributing factor." (PMID 39539911, 2024). "Moreover, in the absence of anti-TPO Abs, the risk of progression to overt hypothyroidism is considered to be low." (PMID 39584162, 2024). "Vitamin B12 deficiency covaried with hypothyroidism irrespective of TPO antibody concentration." (PMID 37758506, 2024). "While previous hypotheses have primarily centered around the possibility of direct autoimmune liver injury as the mechanism through which subclinical hypothyroidism may influence liver steatosis, it is worth considering that anti-TPO antibodies may serve as a marker for genuine thyroid dysfunction." (PMID 39420912, 2024). "Hypothyroidism may also occur for a variety of reasons, the most common being Hashimoto’s disease, a form of hypothyroidism resulting again from autoimmune damage to the thyroid (in this case, autoantibodies directed against the thyroid antigens thyroid peroxidase and thyroglobulin)." (PMID 36830072, 2023). "Although the state of anti-TPO Abs being positive or negative was associated with GD outcomes, defining new titers for each outcome, such as relapse and the development of hypothyroidism, may aid in future predictions." (PMID 37123800, 2023). "The fluctuations of all the ten metabolites induced by anti-TPO antibodies positivity in the present study were in accordance to their previously reported status in hypothyroidism, indicating that anti-TPO antibodies positivity contributes to a metabolic disorder prone to hypothyroidism." (PMID 35331172, 2022). "Anti-TPO antibody subsequently leads to hypothyroxinemia, for which it is necessary that cases with high titer of anti-TPO antibody though euthyroid should be meticulously followed up and screened for to detect development of hypothyroidism or SCH, particularly in future pregnancies." (PMID 35165548, 2022). "However, TPO Ab-positive patients were more likely to develop hypothyroidism." (PMID 35687484, 2022). "So, there was a decrease in the expression of NTSR1 both in the patients with increased levels of anti-Tg and anti-TPO autoantibodies in the serum and patients with hypothyroidism caused by AIT compared to the increased NTSR1 expression in the patients with postoperative hypothyroidism." (PMID 34104248, 2021). "177Lu-DOTATATE therapy may have caused further damage to the thyroid follicles leading to increased exposure of thyroid parenchymal antigens (TPO, Tg), which in turn may have enhanced autoimmune-mediated destruction facilitating rapid progression toward overt hypothyroidism." (PMID 33551992, 2020). "Since both low-grade inflammations and hypothyroidism are known factors that are associated with hypertension, status of hypertension among SCH could act as a determinant factor of the association between TPO-Ab and SCH." (PMID 33007021, 2020). "Therefore, in SAT patients with positive thyroid peroxidase antibody, steroid therapy may be preferred to prevent permanent hypothyroidism." (PMID 31729433, 2019). "Therefore, the positive association between TPOab and triglycerides levels in patients with high thyroid peroxidase levels but low median FT4 levels may be related to hypothyroidism." (PMID 29783969, 2018). "Besides TG, sodium/iodide symporter (NIS) and thyroid peroxidase (TPO) play a central role for thyroid hormone synthesis as evidenced from the fact that genetic abnormalities in any of these key proteins leads to severe hypothyroidism." (PMID 29095946, 2017). "Her severe hypothyroidism might be involved in the development of HE via disturbing the integrity of blood brain barrier, which could have facilitated the transfer of putatively cytotoxic TPO-Abs from blood stream into brain tissue." (PMID 27688922, 2016).